OR51J1 (olfactory receptor family 51 subfamily J member 1)
Description:
Odorant receptor.
Synonyms: OR51J1P; OR51J2; HOR5'Beta8
Gene: Unprocessed pseudogene on chromosome 11 (5,402,597 to 5,403,547, forward strand). Ensembl gene ENSG00000184321.
Subcellular location: Cell membrane
Pathways (Reactome):
Sensory Perception: Expression and translocation of olfactory receptors
Diseases named in the same sentence as OR51J1 in open-access papers:
OR51J1 is named in the same sentence as 5 diseases in open-access papers, as found by Europe PMC text mining. Sharing a sentence is not in itself a finding about the gene and the disease. The quoted sentences say what the papers report.
breast carcinoma (1 paper, 2021). "Furthermore, statistical analysis and qRT-PCR results revealed the potential of OR51J1 as a cancer-associated biomarker for the diagnosis of breast cancer at the mRNA level." (PMID 33566867, 2021). "OR51J1 protein expression in invasive cells, as well as its overall score, showed a significant correlation with ER and PR expression and breast cancer (BC) subtypes." (PMID 33566867, 2021). "This study evaluated OR51J1 mRNA expression level in breast cancer and found the 2.9 fold higher expression in tumors compared to adjacent normal tissues and a low expression level of OR51J1gene was observed in normal tissues." (PMID 33566867, 2021).
melanoma (1 paper, 2021). A malignant, usually aggressive tumor composed of atypical, neoplastic melanocytes. "Although this is the first study on OR51J1, studies on OR51E2, another member of this family, which is expressed in melanoma and prostate cancer revealed that its activation via its ligand, β-ionone, inhibits cancer cell proliferation." (PMID 33566867, 2021).
tumor (2 papers, 2021 to 2023). "The IHC results showed OR51J1 expression on other cellular subtypes than tumor and normal cells, including myoepithelium, fibroblast, and lymphocytes." (PMID 33566867, 2021). "As shown in IHC staining, IDC tumor samples potentially contain different OR51J1 positive cell types." (PMID 33566867, 2021). "According to the IHC results, OR51J1 was expressed in different cellular subtypes including normal, in situ and invasive ductal epithelial cells as well as, myoepithelium, fibroblasts, tumor infiltrating lymphocytes and endothelium." (PMID 33566867, 2021). "Since OR51J1 protein also expressed in other cell types of the samples, for each patient a score was generated that was representative of the protein expression status in invasive cells, tumor infiltrating lymphocytes and endothelial cells." (PMID 33566867, 2021). "For example, OR2W3 upregulation is associated with decreased survival probability, and OR51J1 is overexpressed in HER2-enriched and triple-negative tumors compared to luminal BC but does not correlate with tumor morphologic characteristics." (PMID 37759760, 2023).
cancer (1 paper, 2021). A tumor composed of atypical neoplastic, often pleomorphic cells that invade other tissues. "At first, a statistical approach was used to evaluate the potential of OR51J1 gene as a cancer-associated biomarker." (PMID 33566867, 2021). "Here, a statistical approach using complete data from the human protein atlas database was used to evaluate the potential of OR51J1 gene as a cancer-associated biomarker." (PMID 33566867, 2021). "Statistical analysis revealed that OR51J1 has a high expression level in more than 20 types of cancer tissues without any expression in 44 normal tissues." (PMID 33566867, 2021).
OR51J1 also shares sentences with these, for which no sentence is quoted: prostate carcinoma (1 paper).